MSH6 (mutS homolog 6)
Description:
Component of the post-replicative DNA mismatch repair system (MMR). When bound, MutS alpha bends the DNA helix and shields approximately 20 base pairs, and recognizes single base mismatches and dinucleotide insertion-deletion loops (IDL) in the DNA. After mismatch binding, forms a ternary complex with the MutL alpha heterodimer, which is thought to be responsible for directing the downstream MMR events, including strand discrimination, excision, and resynthesis. ATP binding and hydrolysis play a pivotal role in mismatch repair functions. The ATPase activity associated with MutS alpha regulates binding similar to a molecular switch: mismatched DNA provokes ADP-->ATP exchange, resulting in a discernible conformational transition that converts MutS alpha into a sliding clamp capable of hydrolysis-independent diffusion along the DNA backbone. This transition is crucial for mismatch repair. MutS alpha may also play a role in DNA homologous recombination repair. Recruited on chromatin in G1 and early S phase via its PWWP domain that specifically binds trimethylated 'Lys-36' of histone H3 (H3K36me3): early recruitment to chromatin to be replicated allowing a quick identification of mismatch repair to initiate the DNA mismatch repair reaction.
Synonyms: GTBP; GTMBP; p160; MSH-6; HNPCC5; HSAP; LYNCH5; MMRCS3
Tractability: Small molecule: a structure with a bound ligand is known; it has a high-quality binding pocket. PROTAC: ubiquitination databases record sites on it; its protein half-life has been measured.
Gene: Protein-coding gene on chromosome 2 (47,695,530 to 47,810,109, forward strand). Ensembl gene ENSG00000116062.
Subcellular location: Nucleus; Chromosome
Subcellular location (Human Protein Atlas): Golgi apparatus; Nucleoplasm; Vesicles; Cytosol
Pathways (Reactome):
Disease: Defective Mismatch Repair Associated With MSH6
Gene Ontology:
Molecular function: ADP binding; ATP binding; ATP-dependent activity, acting on DNA; double-stranded DNA binding; enzyme binding; four-way junction DNA binding; guanine/thymine mispair binding; histone H3K36me3 reader activity; magnesium ion binding; mismatched DNA binding; MutLalpha complex binding; oxidized purine DNA binding; protein binding; protein homodimerization activity; single guanine insertion binding; single thymine insertion binding; ATP-dependent DNA damage sensor activity; chromatin binding; damaged DNA binding; DNA binding
Biological process: DNA repair; maintenance of DNA repeat elements; mismatch repair; negative regulation of DNA recombination; determination of adult lifespan; intrinsic apoptotic signaling pathway; intrinsic apoptotic signaling pathway in response to DNA damage; isotype switching; meiotic mismatch repair; response to UV; somatic hypermutation of immunoglobulin genes; somatic recombination of immunoglobulin gene segments; chromatin organization; spermatogenesis
Cellular component: chromosome; MutSalpha complex; nucleoplasm; nucleus; chromatin
Genetic constraint (gnomAD): Loss-of-function variants: 84 observed, 119.79 expected, observed/expected ratio (o/e) 0.7, 90% interval 0.59 to 0.84. The synonymous counts are far from expectation, so gnomAD's model fits this gene poorly and the ratio says little. Missense variants: 2,156 observed, 1,718.4 expected, observed/expected ratio (o/e) 1.25, 90% interval 1.21 to 1.3. Synonymous variants: 829 observed, 612.52 expected, observed/expected ratio (o/e) 1.35, 90% interval 1.28 to 1.43.
Gene-disease validity (ClinGen):
ClinGen rates the evidence that MSH6 causes each of these diseases.
Lynch syndrome (autosomal dominant): Definitive. An autosomal dominant hereditary neoplastic syndrome characterized by the development of colorectal carcinoma and a high risk of developing endometrial carcinoma, gastric carcinoma, ovarian carcinoma, renal pelvis carcinoma, and small intestinal carcinoma.
mismatch repair cancer syndrome 1 (autosomal recessive): Definitive. An autosomal recessive constitutional mismatch repair deficiency syndrome caused by pathogenic variants in the MLH1 mismatch repair gene.
hereditary breast carcinoma (autosomal dominant): Disputed. Breast carcinoma that has developed in relatives of patients with history of breast carcinoma.
Cancer hallmarks: suppression of growth (promotes); escaping immune response to cancer (suppresses); invasion and metastasis (promotes); genome instability and mutations (suppresses); proliferative signalling (promotes); escaping programmed cell death (promotes)
Homologues: Orthologues: chimpanzee MSH6 (99% identical), macaque MSH6 (98% identical), dog MSH6 (93% identical), pig MSH6 (92% identical), rabbit MSH6 (91% identical), guinea pig MSH6 (88% identical), rat Msh6 (86% identical), mouse Msh6 (85% identical), tropical clawed frog msh6 (66% identical), zebrafish msh6 (60% identical), Drosophila melanogaster Msh6 (35% identical), Caenorhabditis elegans msh-6 (30% identical). Paralogues in human: MSH3 (20% identical), MSH5 (14% identical), MSH4 (13% identical).
Diseases named in the same sentence as MSH6 in open-access papers:
MSH6 is named in the same sentence as 319 diseases in open-access papers, as found by Europe PMC text mining. Sharing a sentence is not in itself a finding about the gene and the disease. The quoted sentences say what the papers report.
Lynch syndrome (513 papers, 2007 to 2026). "For example, variants in the DNA mismatch repair (MMR) gene MSH6, identified in individuals suspected of Lynch syndrome, an autosomal dominant condition, are difficult to classify owing to the low cancer penetrance of defects in that gene." (PMID 40282361, 2025). "Further evidence that isolated loss of MSH6 results in a distinct phenotype can be derived from Lynch syndrome (LS), which is caused by germline mutations in any of the MMR genes." (PMID 40651337, 2025). "Four cases of MSS colorectal cancer associated with Lynch syndrome and MSH6 germline mutation were identified." (PMID 40133691, 2025). "Different methodologies, such as single-marker versus multi-marker MSI panels and varied IHC protocols, can affect the detection rates of Lynch syndrome, especially for subtler MSH6 and PMS2 mutations known for their heterogeneous expression." (PMID 40244260, 2025). "MSH6 has been extensively studied for its associations with Lynch syndrome and its role in increasing the risk of several cancers." (PMID 41266338, 2025). "Of note, one EAH/EIN case exhibited isolated MSH6 loss, a hallmark pattern associated with Lynch syndrome." (PMID 41462964, 2025). "One case demonstrated isolated loss of MSH6, a pattern suggestive of a possible germline mutation associated with Lynch syndrome." (PMID 41462964, 2025). "MSH6, a key DNA mismatch repair gene, is highly expressed in PGCs,31,41 and its mutations are linked to Lynch syndrome." (PMID 39999848, 2025). ": Fifty-one year old patient with Lynch syndrome with a right-sided colon adenocarcinoma with a pathogenic MSH6 gene (c." (PMID 40133691, 2025). "Somatic and germline MSH6 mutations, typically in Lynch syndrome, and high tumour mutational burden were detected." (PMID 41085137, 2025). "She had Lynch syndrome, a deleterious germline mutation in MSH6, abundant expression of PD-L1 and high mutation burden (TMB)." (PMID 40133691, 2025). "One case exhibited isolated MSH6 loss, suggesting a potential Lynch syndrome, and another showed combined MSH6/PMS2 loss." (PMID 41462964, 2025). "Medically actionable variants were also identified in two other cancer-related genes, including BRCA2 and MSH6, which are associated with hereditary breast and/or ovarian cancer and Lynch syndrome, respectively." (PMID 40699671, 2025). "In this case study, we present a unique instance of Lynch syndrome-related CCA resulting from a singular MSH6 mutation." (PMID 39161380, 2024).
Lynch syndrome (continued). "There is currently no clear evidence-based evidence and guideline recommendations for the treatment of cholangiocarcinoma associated with Lynch syndrome caused by MSH6 germline mutations." (PMID 39161380, 2024). "As Lynch syndrome results from germline mutations in DNA mismatch repair genes, we examined them and found a germline mutation in MSH6, which accounts for 10–20% of Lynch syndromes in colorectal cancer." (PMID 39101783, 2024). "For example, differences have been reported also within patients with germline variants linked to the Lynch syndrome, with MSH6 mutant tumors showing lower levels of MSI and increased rate of single nucleotide variants, rather than indels." (PMID 38966168, 2024). "The case we report is the first case of Lynch syndrome-related CCA caused by a single MSH6 germline mutation." (PMID 39161380, 2024). "Genomic analysis revealed a Lynch syndrome-related MSH6 germline pathogenic mutation in the patient, specifically a base substitution (c.3964G>T) within the MSH6 gene." (PMID 39161380, 2024). "In this case, genomic panel testing of the tumor specimen revealed mutations in the MLH1 and MSH6 genes, and a history of cancer led to suspicion of Lynch syndrome, which was ultimately diagnosed by germline genetic testing." (PMID 37086325, 2023). "Histopathological work-up revealed the loss of MSH6 expression in the tumor tissue, and germline testing detected a frame-shift mutation in MSH6 gene, implicating Lynch syndrome." (PMID 37569431, 2023). "Unlike cHL, endometrial cancer has been strongly associated with Lynch syndrome and variants in MSH6." (PMID 37910143, 2023). "The proportion of endometrioid and clear-cell histology subtypes was higher in other gene deleterious mutations, related to the frequent Lynch syndrome gene mutation, predominantly in MSH6." (PMID 37174000, 2023). "This case of an MSH6 mosaic variant was identified in a person with a diagnosis of suspected Lynch syndrome/Lynch-like syndrome." (PMID 37318702, 2023). "Specifically, the p.Arg1076Cys MSH6 mutation has been previously reported as pathogenic for Lynch syndrome and various types of cancer, such as lung, pancreatic and breast cancer." (PMID 37175550, 2023). "MSH6 mutations have been implicated in Lynch Syndrome, a condition associated with an elevated risk of colorectal and other cancers." (PMID 38003901, 2023). "Mutations in MSH6 cause approximately 10% of Lynch syndrome cases, and as 3% of EC cases are associated with Lynch syndrome, this would be consistent with the literature and the size of our cohort." (PMID 37175518, 2023). "We identified a likely de novo mosaic MSH6:c.1135_1139del p.Arg379* pathogenic variant in a patient diagnosed with suspected Lynch syndrome/Lynch-like syndrome." (PMID 37318702, 2023). "The frameshift variant we identified in MSH6 is strikingly similar to other pathogenic variants known to cause Lynch syndrome." (PMID 37910143, 2023).
Lynch syndrome (continued). "Of note, the deletions in individuals I22 and I23 as well as three published cases also included the neighboring MSH6 gene, loss-of-function variants in which are responsible for Lynch syndrome (MIM #120 435)." (PMID 34505148, 2022). "Lynch syndrome caused by germline pathogenic variations in MSH6 can have a late onset and is often accompanied by MMS or MSI-L." (PMID 36591511, 2022). "MSH6 (Mut S Homolog 6) encodes a member of the mismatch repair genes family whose pathogenic variants have been associated to Lynch syndrome." (PMID 36035419, 2022). "We identified a three-generation Russian family with Lynch syndrome with a novel germline variant of the MSH6 gene." (PMID 36289196, 2022). "MSH6 is one of the DNA mismatch repair genes, and its mutations play a crucial role in Lynch syndrome, which is an inherited form of CRC." (PMID 36542699, 2022). "Genetic testing showed that the patient’s mother and father were heterozygous carriers of the MSH6 c.3261del mutation, leading to the diagnosis of Lynch syndrome based on the same germline mutation in both parents." (PMID 34425783, 2021). "This indicates the lack of feasibility of using the panel of markers NR21, NR24, NR27, BAT25, BAT26 to study endometrial cancer in patients with Lynch syndrome, which is caused by a mutation in the MSH6 gene." (PMID 33937060, 2021). "The expediency of an immunohistochemical study, rather than a molecular genetic search for microsatellite instability in endometrial tumor samples from patients with Lynch syndrome caused by a mutation in the MSH6 gene, has been demonstrated." (PMID 33937060, 2021). "The MSH6 mutation is important in Lynch syndrome as it has a 5-fold increased risk of endometrial cancer when compared with colorectal cancer." (PMID 34048176, 2021). "A germline, loss of function, splice donor variant (NM_000179.2:c.3438+1G>A, rs267608096) in the Lynch syndrome gene MSH6 was identified in one affected female (case 3)." (PMID 37435187, 2021). "Loss of nuclear expression of MSH6 suggested a high probability of Lynch syndrome and Ambry Genetics panel testing revealed an MSH6 EX3-9del." (PMID 33541411, 2021). "The insertion of 4-bp frameshift (p.Lys1358fs, rs55740729) in MSH6 is known to be a benign variant in Lynch syndrome." (PMID 32948841, 2021). "The mean age of endometrial cancer patients with Lynch syndrome is 47-49 years except those with MSH6 mutation, the mean age is over 50 years." (PMID 34048176, 2021). "A 2006 study reported that Lynch syndrome patients with MSH6 mutation had a 33% lifetime risk of ovarian cancer." (PMID 33182707, 2020). "The risk of Lynch syndrome occurring differs according to the gene, but carriers of the MSH6 pathogenic variant are recognized as having a comparatively high risk of endometrial cancer." (PMID 31286289, 2020). "This is exemplified in Lynch syndrome, which confers increased risks of multiple cancers and results from mutations in DNA mismatch repair genes, including mutS homolog 6 (MSH6)." (PMID 32560344, 2020).